AURKA (aurora kinase A)
Diseases named in the same sentence as AURKA in open-access papers (continued):
Sharing a sentence is not in itself a finding about the gene and the disease.
tumor (continued). "However, both AURKA and AURKB expression were significantly inversely correlated with markers for T-cell infiltration of the tumor: CD3E, CD4, CD8A, LCK, PDCD1 and IFNG." (PMID 33123754, 2021). "Among all these PRGs, AURKA and EZH2 drew our attention because these two genes were hub genes in the network sourced from IPA and were previously considered functional mostly in tumor progression." (PMID 35059393, 2021). "Similarly, overexpression of either WT or mutant NKX3.1 fully abrogated chemotaxis in 22Rv1 cells, underscoring a strong tumor-suppressive function of NKX3.1 in CRPC, whereas AURKA knock-down showed a moderate impact." (PMID 34625072, 2021). "Next, we systematically explored the relationship between the expression of 37 common DEGs in tumor tissues and overall survival (OS) rate of HCC patients in TCGA and constructed a novel prognostic model composed of five genes (AURKA, PZP, RACGAP1, ACOT12 and LCAT)." (PMID 34336648, 2021). "In this tumour type, hypoxia induction of HIF-1α and AURKA might be involved in promoting HCC proliferation." (PMID 34062959, 2021). "IHC results showed that the CAV1, AKR1C3, and TRIB3 protein expression levels were significantly higher in HNSCC tumor tissues (P < 0.05), but the difference in AURKA was not significant (P = 0.144)." (PMID 34539737, 2021). "Much attention is currently given to the proliferation-related mechanism of BC due to the functional specificity of BIRC5/survivin in activating Aurora B kinase within the chromosomal passenger complex, and its co-localization with other tumor proliferation genes MKI67, CCNB1, and AURKA." (PMID 34064473, 2021). "One study showed that AURKA and MDM2 antagonism with MLN8237 and Nutlin-3 halted melanoma growth by inducing growth arrest and senescence, limiting the lifespans of senescent cells, and enhancing tumor immune infiltration and clearance." (PMID 33451333, 2021). "In our study, we observed that Ili-A could reduce EZH2 protein and mRNA level and the expression of the downstream AURKA/PLK1 gene, which contribute to the anti-tumor effects against CRPC." (PMID 34776951, 2021). "We were able to determine binding of APA to AURKA, activation of phospho-AURKA in slow but not rapid acetylator tumor cells, and mitotic arrest along with formation of multipolar mitotic spindles in CRC cells expressing the slow acetylator variant." (PMID 33384440, 2020). "We also observed the same result in mice tumor tissues where α-tubulin level was overall reduced in RB1−/− tumors, and was further reduced by the AURKA inhibitor treatment or AURKA silencing." (PMID 33037191, 2020). "Thus, phospho-resistant SPOP has higher tumor-suppressing potential as compared to wild type SPOP, presumably due to its resistance to AURKA-mediated degradation." (PMID 33158056, 2020). "AURKA overexpression could also increase the expression of MMP-2, MMP-7, MMP-9, leading to tumor metastasis by degrading extracellular matrix proteins." (PMID 31706255, 2019). "Moreover, over-expression of Aurora kinase A (Aur-A) and FOXM1 was observed in PTX-resistant TNBC cells, suggesting the role of Aur-A in the protection of tumor cells against PTX." (PMID 31783552, 2019). "AURKA signals through C-MYC to induce telomerase, supporting tumor immortalization." (PMID 31254157, 2019). "Natural killer (NK)-cell-derived exosomes carrying the tumor suppressor miR-186 induced cytotoxicity when internalized by MYCN-amplified NB cell lines, through an inhibitory action on MYCN expression, Aurora Kinase A (AURKA), and transforming growth factor (TGF)-β-receptors 1–2." (PMID 31533332, 2019). "Collectively, our data suggest that BET inhibition may be combined with Aurora Kinase A inhibition to increase the efficacy of monotherapy, especially in cases where BET inhibition lacks a substantial effect on tumor cells." (PMID 31754113, 2019).
tumor (continued). "Dual inhibition of EGFR and AURKA could offer synergistic mechanisms to overcome resistance and suppress tumours such as SCCHN and NSCLC where redundancy in EGFR and AURKA signaling is observed." (PMID 29115879, 2018). "Our present results reveal that tivozanib inhibits p-PLK1 and decreases Aurora kinase A in the GBM cells, suggesting that tivozanib might have anti-tumour activity in GICs cells." (PMID 28287096, 2017). "In addition, immunohistochemistry revealed a reduction in AURKA, FOXM1 and Nanog staining in Dox-treated tumours, compared with the DMSO-treated controls." (PMID 28114286, 2017). "Besides, a group recently demonstrated that daurinol, a novel topoisomerase inhibitor, can inhibit the transcriptional activity of both AURKA and AURKB, which increased the radio-sensitivity of tumor cells in vivo and in vitro." (PMID 28147341, 2017). "By treating with 2 μM U0126 for 2 days, the invasion distance promoted by exogenous AURKA was reversed in MCF-10A cells, suggesting that ERK acted as a downstream of AURKA to modulate collective cohorts formation during tumor local invasion." (PMID 28592839, 2017). "IHC staining of subcutaneous tumour sections confirmed that OHT regulated the subcellular localization of AURKA (image 2/4 compared with image 1/3), and that VX-680 suppressed AURKA phosphorylation at T288 (image 3/4 compared with image 1/2)." (PMID 26782714, 2016). "In addition, VX680, TAE226, Omipalisib and Triciribine, inhibitors of AURKA, FAK, PI3k and Akt, respectively, reduced LSCC cell mobility, migration and invasion and lead to tumor regression." (PMID 27356739, 2016). "In order to determine the functional role of these kinases in KRAS-induced transformation, we generated KRAS-positive A549 and H358 cells with stable and inducible shRNA-mediated knockdown of AURKA or AURKB and evaluated transformation in vitro and tumor growth in vivo." (PMID 26842935, 2016). "Also, combined targeting of the mTOR pathway and the mitotic checkpoint protein aurora kinase A, using rapamycin + MLN8237, synergistically reduced uLMS cell growth in vitro, as well as tumor growth in an in vivo model." (PMID 26576131, 2015). "While AURKA expression has been shown to be a more powerful prognosticator than KI67, KI67 has been advocated as the marker of choice for measuring and monitoring tumour proliferation." (PMID 25472026, 2014). "The tumor mass harvested from the BEL-7402 xenograft study was prepared into paraffin embedded slides and subjected to immunohistochemisty for visualizing angiogenesis maker human CD31 and Aurora kinase A activity marker phospho-Aurora A (T288)." (PMID 23755206, 2013). "Among patients with KRAS wild-type tumours, the median OS was not reached for high AURKA-CN compared with 18.8 months for the group with low AURKA-CN tumours (HR=0.14, 95% CI: 0.038–0.514, P=0.003)." (PMID 22240781, 2012).
tumor (continued). "In summary, YBX1 promotes tumor progression through its transcription factor activity, exerting its effects via various downstream targets such as MUC1, CDC25a, NANOG, Kindlin-2, G3BP1, AURKA, SPP1, the EGFR-RAS-MAPK axis, CORO1C, among others, depending on the specific tumor type." (PMID 40799245, 2025). "Evaluating disruptions in AURKA/NMYC in this manner could be useful in the context of clinical trials to either stratify patients without the need for tumour biopsies or for longitudinal monitoring to assess response to these treatments." (PMID 39840448, 2025). "Thus, targeting them as well as AURKA could provide therapeutic benefits, particularly in PTEN mutant LGG, PRAD, SARC, and SKCM tumours." (PMID 40775769, 2025). "Additionally, the negative correlation between GOLPH3 and GLI4, as well as AURKA, becomes significantly weaker in tumor samples." (PMID 40136480, 2025). "Further functional assays demonstrated that knockdown of AURKA significantly impaired the proliferation and induced ferroptosis of ES cells, while overexpression of NPM1 partly reversed the proliferation arrest and ferroptosis of tumor cells induced by AURKA knockdown." (PMID 38287009, 2024). "Nonetheless, numerous mechanisms indirectly targeting this pathway, including the use of aurora kinase A (AURKA) and bromodomain and extra-terminal motif (BET) inhibitors, to name a few, provide viable therapeutic opportunities to decrease MYCN expression and reduce tumor volume." (PMID 38525424, 2024). "Interestingly, we encountered an inverse modulation of AURKA and TOP2A in tumor and normal breast cells, which could constitute the basis for treatment selectivity." (PMID 37888205, 2023). "Concerning copy number aberrations (CNAs), the top amplified genes in the samples from the primary tumor were ERBB2 (6/19, 32%), AURKA, PPM1D (4/19, 21%), and FGFR1 (3/19, 16%), while in the metastatic samples ERBB2 (7/17, 41%), CDK12, FGFR1 (4/17, 24%), and AURKA, MDM4, MYC (3/17, 18%)." (PMID 36717329, 2023). "However, neither the genes encoding AURKA and USP8 nor those encoding USP48, BRAF, BRG1 and CABLES were affected in this tumor." (PMID 35563252, 2022). "In preclinical studies, inhibition of AURKA by MLN8237 (alisertib) efficiently induced N-MYC degradation, G2/M cell cycle arrest, apoptosis, and reduction in phosphorylation of the Aurora kinase substrate histone H3 in NB cells, and induced tumor regression in NB xenografts mice." (PMID 36551697, 2022). "Furthermore, proline hydroxylation is important for the tumour suppression activity of DYRK1 toward the regulation of VHL E3 ligase activity and hence, the stability of VHL substrates critical for cell cycle progression such as HIF-2α, AURKA, and cyclin D1." (PMID 34062959, 2021). "Finally, a combination of an AURKA inhibitor, MLN8237 (alisertib) with NVP-BEZ235 in a 786-0 VHL-null mouse xenograft model of RCC dramatically reduced tumor burden, highlighting the potential for co-inhibition of AKT, mTOR and AURKA as a clinical intervention strategy." (PMID 34002003, 2021). "Moreover, we assessed the AURKA expression in GC tissues, adjacent non-tumor tissues and normal gastric samples and evaluated its correlation with clinicopathological characteristics." (PMID 31871591, 2019). "Furthermore, it has been demonstrated that the tumor suppressor miR-26a-5p directly targets LIN28B and AURKA in HB cells, which highlights the relevance of the LIN28B-RAN-AURKA axis in the pathogenesis of this disease and the role of miR-26a-5p as a repressor of this signaling." (PMID 30909459, 2019). "Notably, these studies provided the rationale for combinatorial approaches involving either inhibition of DDR1 and Notch signaling or inhibition of the FOSL1 target AURKA and MEK, both of which blocked tumor initiation and progression as well as induced tumor regression." (PMID 29455666, 2018).
tumor (continued). "Although it is known that AURKA regulation of mitosis and centrosome function plays an important role in OC biology, there remains a large gap in our knowledge of alternative, non-mitotic functions of this kinase in tumor cells." (PMID 28881569, 2017). "In addition, AURKA overexpression can significantly enhance the expression of matrix metalloproteinases (MMP)-2, MMP-7 and MMP-10, leading to degradation of extracellular matrix proteins, which stimulates tumor cell mobility and metastasis." (PMID 28147341, 2017). "The fact that alisertib, as a single agent or as part of a combination therapy regimen showed clinical activity in a subset of patients, underscores the need to improve our understanding of AURKA-regulated pathways that mediate tumor progression, including novel non-mitotic functions." (PMID 28881569, 2017). "However, the molecular mechanisms whereby oncogenic KRAS regulated AURKA expression and its clinical and functional role in KRAS-driven tumours were largely unknown." (PMID 28220783, 2017). "Nonetheless, AURKA inhibition did not lead to tumor regression." (PMID 26842935, 2016). "AurkA has long been recognized as an oncogene, due to its overexpression and amplification in several human cancers; however, it is unlikely to act as oncoprotein, since its over expression neither transforms primary cells nor leads to tumor formation." (PMID 26322273, 2015). "Among the seven tumours with low AURKA-CN, none were positive for phosphorylated T-288." (PMID 22240781, 2012). "AURKA-CN level did not affect outcomes among patients with KRAS mutant tumours." (PMID 22240781, 2012). "However in our study, among patients with KRAS wild-type tumours, the impact of high AURKA-CN level was most pronounced in patients who did not receive cetuximab." (PMID 22240781, 2012). "Finally, the gene-set #2 also contained several tumour suppressors (EPHA3 and EPHB2) and proto-oncogenes (AKT1, AURKA, ETV6, MITF and PIK3CA), which expands on the observed enrichment of the immune response and suggests that this gene-set has a critical role in breast tumorigenesis." (PMID 19826428, 2009). "We have also shown that almost all tumours show higher levels of AURKB (and AURKA) expression than their matched normal lung tissues, which could therefore simply be a consequence of a higher proliferative index, or be typical of the progenitor cell and atypical of the bulk of normal lung cells." (PMID 16222316, 2005). "In recent years, interest has also grown in the direction of non-mitotic and kinase-independent AurkA roles that are now emerging as a route for both tumour onset and progression, and may partly account for the poor efficacy of AurkA inhibitors in clinical trials." (PMID 39195284, 2024). "In addition, by targeting AURKA, SHD may inhibit tumor angiogenesis in breast cancer." (PMID 35699421, 2022). "Interestingly, from these 17 significant pairs (adjusted p-value ≤ 0.05) several downregulated tumour-suppressor miRNAs (e.g., miR-let-7c, miR-139, miR-145 or miR-195) appeared to regulate oncogenic genes related to the cell cycle and DDR pathways (BUB1B, AURKA, BIRC5, CENPK, BRCA1 and CHEK1)." (PMID 28387377, 2017). "Interestingly, Aurora kinase A is dramatically overexpressed in MPNST cell lines and its inhibition may limit tumor cell growth; additionally, in vitro targeting of SOX9 (Sex-determining-region Y-box 9) by shRNA (short hairpin RNA) reduces MPNST cell survival and increases death." (PMID 24303016, 2013).
tumor (continued). "Thus, 343 isolates showed activity against the tumor cell line (16.8%), 101 against C. albicans ATCC 10231(4.9%), 198 against S. aureus ATCC 51650 (9.7%), 59 against PTP1B (2.9%); but only 3 and 9 strains were active against caspase 3, and aurora kinase A, respectively." (PMID 19370169, 2009). "The re-expression of TPX2WT, but not TPX2K249R, facilitated the in vivo tumour growth of HepG2 xenografts with endogenous TPX2 knockdown, which was abolished by treatment with both LDHA inhibitor, GSK2837808A, and AURKA inhibitor, alisertib." (PMID 40107714, 2025). "WNT4 had decreased expression (logFC = −1.6), and the expression of seven mRNAs (CDK4, MAPK1, TGFB, ZEB2, AURKA, SOX4, and ADAM9) in tumor samples was not notably different from that in the group of normal tissues." (PMID 35453574, 2022). "The tumor suppressor SMAD4 interacts with AURKA and inhibits the expression of AURKA via proteasomal degradation which is independent of TGFβ signaling." (PMID 33451333, 2021). "Blocking AURKA nuclear localization (in the absence of OHT, group 2) attenuated tumour growth in xenograft model." (PMID 26782714, 2016). "Our study revealed that AURKA is a bona fide marker of the severity of the disease whereas PLK1 and MAP9 expression does not correlate with the tumor grade." (PMID 24876664, 2014). "The relative expression levels of CDKN3, MKI67, CEP55, SPAG5, AURKA, TOP2A were consistent with the results of bioinformatics analysis (P < 0.05), while the expression levels of UBE2C, CHEK1 and BIRC5 in tumor samples were not significantly different from adjacent normal samples." (PMID 35178291, 2022). "However, the distribution frequency of AURKA SNP rs6024836 did not reveal a significant difference between the entire study group and the wild-type EGFR group concerning tumor stage, TNM status, or cell differentiation condition." (PMID 33050100, 2020). "The classifier could not be applied to predict survival based on expression of AURKA, PTGS2 and MMP9 in the primary tumor." (PMID 26497206, 2016). "Notably, the expression level of AURKA in co-cultured HCC827 cells did not change compared with the mono-cultured HCC827 cells in the absence of gefitinib, suggesting that fibroblasts promoted tumor cell survival only in the presence of gefitinib." (PMID 25634113, 2015).
adenocarcinoma (13 papers, 2011 to 2024). A common cancer characterized by the presence of malignant glandular cells. "Compared with adenocarcinoma cell LNCaP and 22Rv1, both AURKA and N-Myc protein level were much higher in LNCaP-NE and 22Rv1-NE as well as in PC-3/DU145." (PMID 37385990, 2023). "Aurora kinase A (AURKA), a G2→M regulating cell cycle kinase, and delta-like protein 3 (DLL3), a cell surface notch signal inhibiting ligand, are other examples of proteins enriched in NEPC and its small-cell variant compared to adenocarcinoma." (PMID 35205640, 2022). "Amplification of MYCN and AURKA (Aurora Kinase A) genes has also been observed in NEPC, with amplification of both genes seen in approximately 40% of NEPC cases and 5% of adenocarcinoma tumors." (PMID 37761978, 2023). "The expression of AURKA and AURKB was higher in CRPC of neuroendocrine type than in CRPC adenocarcinoma, consistent with the poor prognosis for patients with CRPC of neuroendocrine type." (PMID 35853811, 2022). "Using next-generation sequencing as a tool to define the transcriptome of both NE- and adeno-PCs, we discovered that the vast majority of NEPC over-express the cell cycle kinase AURKA (Aurora kinase A) and MYCN compared to adenocarcinoma." (PMID 24724054, 2014). "Moreover, the expression of AURKA and AURKB was higher in CRPC of the neuroendocrine type than in CRPC adenocarcinoma, consistent with the poor prognosis for patients with CRPC of the neuroendocrine type." (PMID 35853811, 2022). "For example, a AURKA inhibitor was developed to specifically suppress the NEPC growth without influencing the adenocarcinoma cells growth." (PMID 31189930, 2019).